NLRP3 (NLR family pyrin domain containing 3)
Diseases named in the same sentence as NLRP3 in open-access papers (continued):
Sharing a sentence is not in itself a finding about the gene and the disease.
cardiovascular diseases (continued). "We further examined the involvement of pyroptosis, which is closely associated with NLRP3 inflammasome, in cardiovascular diseases." (PMID 34381021, 2021). "Globally, these findings support a growing evidence suggesting that the activation of the NLRP3 inflammasome actively contributes to the inflammatory response that drives cardiovascular diseases, particularly when associated to metabolic alterations." (PMID 32214150, 2020). "Our study implicates an essential axis of ROS‐NLRP3‐IL‐1β pathway in cardiovascular diseases associated with ageing, which reveals a potentially novel option involving use of ROS inhibitors, which target priming and activation steps of NLRP3 inflammasomes." (PMID 33022900, 2020). "We made a mini-review on the association of regulatory mechanisms of NLRP3 inflammasome with the development of cardiovascular diseases systematically based on the recent research studies." (PMID 32377298, 2020). "Despite the potential significance of NLRP3 inflammasome in the pathogenesis of several diseases, emerging evidence suggests that NLRP3 inflammasome events are associated with cardiovascular diseases conditions." (PMID 32377298, 2020). "For instance, IL-6 is a known downstream target of IL-1β, consistently increased in patients with NLRP3 inflammasome-mediated conditions, such as cardiovascular disease and associated with clinical outcomes." (PMID 30483114, 2018). "Furthermore, treatment of empagliflozin in T2DM patients at high risk of cardiovascular disease led to a reduction in IL-1β secretion due to reduced NLRP3 inflammasome activation." (PMID 39843817, 2025). "Overall, the investigation of the close association between MAVS and the NLRP3 inflammasome in cardiovascular diseases provides us with deeper insights into the immune mechanisms underlying these conditions, while also offering potential drugs targeted NLRP3 for future therapeutic strategies." (PMID 40040697, 2025). "In the last ten years, the overexpression of NLRP3 and the activation of the inflammasome have been associated with radiation-induced lung inflammation, oral mucositis and skin lesions, as well as cardiovascular diseases." (PMID 41272654, 2025). "Moreover, cardiovascular diseases have also been identified to be associated with the aberrant activation of NLRP3 inflammasome and oxidative stress." (PMID 40643515, 2025). "This study suggests that HIV infection may exacerbate the risk of cardiovascular disease in PWH by activating NLRP3." (PMID 38785555, 2024). "Recently, the importance of the NLRP3 inflammasome in cardiovascular disease-related inflammation has been extensively studied, and it is known that NLRP3 inflammasome increases the risk of cardiovascular disease by increasing the activation and release of IL-1 family cytokines." (PMID 37810823, 2023). "Interestingly, the ability of SGLT2i to reduce inflammatory cytokines in patients with cardiovascular disease was implicated with the inactivation of NLR family pyrin domain containing 3 (NLRP3) inflammasome by SGLT2i via ketone bodies." (PMID 36971696, 2023). "The involvement of NLRP3 MyD-88 and some DAMPs in ICIs-associated cardiovascular disease was seen." (PMID 36158826, 2022). "Moreover, in both studies, it has been observed that patients with typical cardiovascular disease risk factors present higher levels of NLRP3 inflammasome activation." (PMID 35204152, 2022). "NLRP3 inflammasome is a hub where Btk is linked to cardiovascular disease." (PMID 35296647, 2022). "NLRP3 inflamamsome may be involved in development of cardiovascular disorders associated with metabolic diseases." (PMID 34123416, 2021). "This mini-review focuses on the association of regulatory mechanisms of NLRP3 inflammasome with the development of cardiovascular diseases, which may supply some important clues for future therapies and novel drug targets for cardiovascular diseases." (PMID 32377298, 2020).
cardiovascular diseases (continued). "Many studies have examined the association between the NLRP3 genotypes and cardiovascular disease." (PMID 32313131, 2020). "While NLRP3‐inflammasome has been implicated in cardiovascular diseases, its role in physiological cardiac aging is largely unknown." (PMID 31625260, 2020). "Thus, the NLRP3 inflammasome is closely associated with various cardiovascular diseases, and small molecule inhibitors targeting NLRP3 may offer significant therapeutic potential in clinical practice." (PMID 39223947, 2024). "Moreover, HIV infection in macrophages and peripheral blood mononuclear cells (PBMCs) from PWH showed increased expression levels of NLRP3 inflammasome components and downstream cytokines (including caspase-1, IL-1β, and IL-18), which correlated with various genes linked to cardiovascular disease." (PMID 38785555, 2024). "Thus, the NLRP3 inflammasome is a complex that is associated with cardiovascular disease." (PMID 35035656, 2022). "Related studies have shown that excessive ROS-induced NLRP3 inflammasome activation leading to pyroptosis is widespread in cardiovascular diseases." (PMID 40478791, 2025). "This comparative view further reinforces the rationale for selectively targeting NLRP3 in radiation-induced cardiovascular diseases." (PMID 41272654, 2025). "The NLRP3 inflammasome has been identified as an important biomarker in many cardiovascular diseases, including AF, with the crosstalk between the PI3K/AKT/mTOR pathway and the NLRP3 inflammasome potentially influencing the autophagy response in AF." (PMID 40498015, 2025). "The NLRP3 inflammasome and IL-1 cytokines are central to the development and progression of cardiovascular diseases, including inflammatory heart conditions." (PMID 40940808, 2025). "NLRP3 inhibitors under clinical development in cardiovascular diseases: name and chemical structure." (PMID 40040697, 2025). "Numerous studies have been conducted to investigate potential treatment approaches that target the inflammatory response since the function of the NLRP3 inflammasome in cardiovascular diseases has been increasingly validated." (PMID 40079000, 2025). "Another NLRP3 inhibitor reported in the literature to be beneficial in cardiovascular diseases is Bay 11-7082." (PMID 41272654, 2025). "Chronic low-grade inflammation disrupts vascular homeostasis and promotes age-related cardiovascular disease by activating the NF-κB and NLRP3 inflammasome pathways." (PMID 40940785, 2025). "Given the central role of NLRP3/IL-1β in cardiovascular diseases, it is likely that the NLRP3 inflammasome and IL-1β signalling also contribute to the cardiac involvement in MIS-A." (PMID 39775145, 2025). "Colchicine is an anti-inflammatory alkaloid that disrupts microtubule formation and inhibits nucleotide-binding domain-like receptor protein 3 (NLRP3) inflammasome activation, thereby targeting key inflammatory pathways involved in cardiovascular diseases." (PMID 40528106, 2025). "In autophagy-impaired cardiovascular disease states, the combination of NLRP3 inflammasome and mitochondrial ROS can elevate cytosolic mtDNA leakage, thereby exacerbating cytokine release." (PMID 39861173, 2025). "Accumulating evidence has demonstrated that NLRP3 inflammasome activation-mediated pyroptosis is involved in many cardiovascular diseases." (PMID 41503885, 2025). "Future research on MI will focus on a deeper understanding of the role of the NLRP3 inflammasome in different cardiovascular diseases and the development of more specific and effective NLRP3-targeted therapeutic strategies." (PMID 40587711, 2025). "We summarize key findings on the role of radiation in modulating the NLRP3 inflammasome and inducing cardiovascular disease, providing a detailed overview of NLRP3 inflammasome functions in different radiation-induced cardiovascular diseases." (PMID 41272654, 2025).
cardiovascular diseases (continued). "One of the best studied connections between the lysosomal-autophagy pathways and inflammation is the NLRP3 inflammasome pathway, which plays a key role in the progression of cardiovascular diseases 22,39." (PMID 40166006, 2025). "Taken together, these results highlight the potential efficacy of inhibitors of NLRP3 or its downstream pathways in improving or preventing radiation-induced cardiovascular disease." (PMID 41272654, 2025). "NLRP3 inflammasome activation drives inflammatory infiltration within myocardial tissues, and is a major contributor to progression of cardiovascular disorders." (PMID 40064794, 2025). "NLRP3 inflammasome emerges as a fundamental molecular nexus in the pathophysiological bridge between periodontal and cardiovascular pathologies." (PMID 40869031, 2025). "It is well known that NLRP3 inflammasome plays a key role in the inflammatory response in various cardiovascular diseases." (PMID 40384971, 2025). "The involvement of the NLRP3 inflammasome has been observed in various cardiovascular diseases (CVD)." (PMID 38681198, 2024). "Natural products are also acknowledged as valuable resources in cardiovascular diseases treatment, with some extracts found to inhibit NLRP3 inflammasome." (PMID 39508038, 2024). "Two others were large cohort studies investigating NLRP3 inflammasome-based anti-inflammatory therapy for cardiovascular diseases." (PMID 39022620, 2024). "Clusters 2, 3, 4, and 5 predominantly involved the cellular mechanisms and molecular pathways by which NLRP3 inflammasomes contribute to cardiovascular diseases." (PMID 39022620, 2024). "Further investigations into the relationship between NLRP3 inflammasome inhibitory drugs and the progression of cardiovascular diseases are warranted to advance the development of pertinent clinical therapeutics." (PMID 38317229, 2024). "This study aimed to use visualization analysis software (“CiteSpace” and “Bibliometrix”) to explore the research trends and hotspots related to the NLRP3 inflammasome in cardiovascular disease over the past 12 years." (PMID 39022620, 2024). "The NLRP3 inflammasome-mediated pyroptosis has received widespread attention, and it has been found to play a crucial role in the pathogenesis of cardiovascular diseases." (PMID 39121041, 2024). "This study utilized Bibliometrix, CiteSpace, and Microsoft Excel to analyze 516 articles retrieved from the Web of Science Core Collection, focusing on NLRP3 inflammasome research in cardiovascular diseases." (PMID 39022620, 2024). "Bibliometric analysis reveals a promising and rapidly growing field of research investigating the NLRP3 inflammasome in cardiovascular diseases." (PMID 39022620, 2024). "Keyword analysis further highlighted the pivotal roles of NF-κB, oxidative stress, and CRP in NLRP3 inflammasome-related cardiovascular diseases." (PMID 39022620, 2024). "The search query used the keywords “[“CVD” OR “cardiovascular disease”] AND [“NLRP3 inflammasome “OR “NLRP3”]”." (PMID 39022620, 2024). "Several small molecules, such as colchicine, CY‐09,118 and OLT1177,119 have been identified as NLRP3 inhibitors, demonstrating protective effects in cardiovascular diseases." (PMID 39223947, 2024). "This article aims to comprehensively review the intricate correlation between cardiovascular disorders and NLRP3 inflammasome, delving into the regulatory functions exerted by sympathetic and vagus nerves within the ANS on NLRP3 inflammasome." (PMID 38650918, 2024). "Targeting the NLRP3/interleukin-1β innate immunity in cardiovascular disease has gained substantial interest, yielding advancements in both preclinical and the first clinical trials alike 7,29–32." (PMID 38914598, 2024). "This upward trajectory suggested that NLRP3 inflammasome research in cardiovascular diseases has reached a relatively mature stage of development." (PMID 39022620, 2024).
cardiovascular diseases (continued). "It is in phase 2 clinical trials for a number of NLRP3-associated diseases, such as symptomatic knee osteoarthritis (NCT04886258) and cardiovascular diseases (NCT06031844, NCT06097663)." (PMID 38945951, 2024). "Recently, inflammatory cytokine production, followed by activation of the NLRP3 inflammasome, has been identified as a target for cardiovascular diseases." (PMID 38274622, 2024). "Since 2017, research has increasingly focused on the role of NLRP3 inflammasome-mediated inflammatory responses in the development and progression of cardiovascular disease." (PMID 39022620, 2024). "This study provides valuable insights into the research hotspots and emerging trends of the NLRP3 inflammasome in cardiovascular disease." (PMID 39022620, 2024). "A possible mechanism for secondary prevention of cardiovascular diseases involves colchicine, which plays a vital role in reducing intracellular inflammatory responses and activating NLRP3 inflammation." (PMID 38274622, 2024). "NLRP3 inflammasome is an essential intracellular multiprotein complex and plays an important role in driving inflammatory responses in cardiovascular diseases." (PMID 39121041, 2024). "The NLRP3 inflammasome is an important sensor and indicator not only of inflammatory immune disorders but also of metabolic disorders, cardiovascular diseases, and respiratory ailments, which primarily constitute lifestyle diseases." (PMID 38945951, 2024). "This study utilized bibliometric methods to analyze research on the NLRP3 inflammasome in cardiovascular diseases retrieved from the Web of Science Core Collection." (PMID 39022620, 2024). "Oral inhibitors targeting the NLRP3 inflammasome have been considered as prospective therapeutic agents for the treatment of cardiovascular diseases." (PMID 39121041, 2024). "NLRP3-mediated pyroptosis pathway are widely studied, and related inhibitors are well used in clinical practice in cardiovascular disease." (PMID 38750444, 2024). "This study aimed to analyze the research status of the NLRP3 inflammasome in cardiovascular disease and provide research directions for further exploration in this field." (PMID 39022620, 2024). "Given that the MAPK signaling pathway plays essential role in various cardiovascular diseases and has been shown to regulate NLRP3, we further explored the effects of mulberry extract on this pathway." (PMID 37324843, 2023). "When considered collectively, preclinical research findings imply that statins have the potential to be an efficient therapeutic and prevention approach for cardiovascular disease by controlling NLRP3 activation." (PMID 37175869, 2023). "Mcc950, which is a novel inhibitor of the NLRP3 inflammasome, can be applied to treat various kinds of cardiovascular diseases." (PMID 37008319, 2023). "The activation of the NLRP3 inflammasome aggravates oxidative stress and vascular endothelial dysfunction, and accelerates the pathological process of cardiovascular diseases." (PMID 37370025, 2023). "Recent studies have also identified the presence of genetically determined systemic inflammation in cardiovascular diseases, highlighting the NLRP3 inflammasome as a promising therapeutic target." (PMID 38203704, 2023). "NOD-like receptor protein 3 (NLRP3) inflammasome, a potential therapeutic target for a variety of cardiovascular diseases, can sense pathogen-related molecular patterns and endogenous danger signals." (PMID 37138870, 2023). "Activation of the NLRP3 inflammasome and our innate immune response, is a major perpetrator of inflammatory damage in both CKD and cardiovascular disease (CVD), with NLRP3 activation linked to renal injury-induced cardiac dysfunction." (PMID 37770948, 2023). "The development of therapeutic compounds that specifically target the activation of NLRP3 inflammasome and pyroptosis holds promise for the mitigation of cardiovascular diseases induced by pyroptosis." (PMID 37765083, 2023).
cardiovascular diseases (continued). "In particular, the NLRP3 inflammasome activation plays an important role in the pathophysiology of cardiovascular disease." (PMID 37498354, 2023). "In line with our studies, similar to the NLRP3-KO mice, the SPARC-deficient mice are also protected from cardiovascular disease with lower inflammation and reduced macrophage infiltration." (PMID 37781916, 2023). "As the mechanism of HS-mediated cerebrovascular or cardiovascular diseases, IL-1 cytokines are triggered by various environmental factors, and NLR family pyrin domain containing 3 (NLRP3) is highly expressed in atherosclerotic plaques." (PMID 36766606, 2023). "LncRNA has been confirmed to show a tight correlation with NLRP3 inflammasome-mediated pyroptosis in cardiovascular diseases." (PMID 37158944, 2023). "Based on many anti-inflammatory trials, only therapies acting on the NLRP3 inflammasome, or interleukin 1beta, showed benefits on cardiovascular disease." (PMID 35837017, 2022). "Expanding translational research using selective NLRP3 inhibitors is necessary to fully evaluate the potential of NLRP3 inflammasome inhibition in cardiovascular disease." (PMID 35273164, 2022). "Studies have shown that pyroptosis regulated by the NLRP3 inflammasome is closely related to the progression of cardiovascular disease." (PMID 35033112, 2022). "Targeting the NLRP3 inflammasome using Btk has received attention as another feasible approach for the treatment of cardiovascular disease." (PMID 35296647, 2022). "Robust evidence has demonstrated a critical role for the NLRP3 inflammasome in the pathophysiology of various cardiovascular diseases (CVDs) owing to its ability to secrete the pro-inflammatory cytokines IL-1β and IL-18." (PMID 35806076, 2022). "The CANTOS trial highlighted the importance of direct anti-inflammatory therapies targeting the NLRP3 inflammasome-derived inflammatory cytokine IL-1β in secondary cardiovascular disease prevention." (PMID 36111168, 2022). "Above all, NLRP3, as the initiating signal of pyroptosis, is a potential therapeutic target for tackling cardiovascular diseases." (PMID 35865939, 2022). "As promising targets for cardiovascular diseases, NLRP3 and IL-1 inhibitors have achieved positive clinical effects; it is of great clinical significance to develop more novel and specific inhibitors." (PMID 35464402, 2022). "Clinical studies are required to elucidate the effects of ICIs on myocardial and vascular inflammation and confirms the role of NLRP3 and Myd88 in progression of ICIs-mediated cardiovascular diseases." (PMID 36158826, 2022). "The activation of NLRP3 inflammasome in macrophages has been proven to play a crucial role in the development of cardiovascular diseases." (PMID 36618426, 2022). "This review focuses on the activation and regulation mechanism of inflammasomes, the role of inflammasomes in cardiovascular diseases, and the research progress of targeting NLRP3 inflammasome and IL-1β for related disease intervention." (PMID 35464402, 2022). "Emerging evidence highlights the involvement of NLRP3 inflammasome-mediated inflammation in the initiation and progression of metabolic disorders and cardiovascular diseases." (PMID 36111168, 2022). "It has been observed that the NLRP3 inflammasome is critical in the pathological progression of various cardiovascular diseases including AS35." (PMID 35974041, 2022). "MCC950, a specific NACHT, LRR, and PYD domains-containing protein 3 (NLRP3) inhibitor, has been reported to play a role in various cardiovascular diseases." (PMID 35287557, 2022). "ROS and ROS-associated proteins can act as damage associated molecular pattern molecules (DAMPs) to activate the NACHT, LRR, and PYD domains-containing protein 3 (NLRP3) inflammasome in cardiovascular diseases." (PMID 36588561, 2022).